BACH1 (BACH transcriptional regulator 1)
Diseases named in the same sentence as BACH1 in open-access papers (continued):
Sharing a sentence is not in itself a finding about the gene and the disease.
lung cancer (continued). "Lung cancer cell lines which were isolated and established from the Kras mutant mice with antioxidant treatment showed that antioxidant reduced reactive oxygen species (ROS) levels and stabilized Bach1 protein levels through heme, while BACH1 transcripts were not altered." (PMID 33809182, 2021). "Although FBXO22 was proposed as a specific ubiquitin E3 for SCF-mediated BACH1 degradation in lung cancer cells, experimental evidence for FBXO22-mediated BACH1 ubiquitination in vitro have not yet been obtained." (PMID 40263598, 2025).
breast carcinoma (69 papers, 2005 to 2026). "When we used a patient cohort of 130, higher levels of BACH1 were linked to tumors that were larger in size and a specific type of breast cancer called basal-like breast cancer." (PMID 40710214, 2025). "In breast cancer, relatively high levels of BACH1 cause increased migration and invasion, intravasation, and in vivo metastasis by upregulating the transcriptional expression of matrix metalloproteinase 9 (MMP9) and C-X-C chemokine receptor type 4 (CXCR4)." (PMID 40710214, 2025). "Because race is an important indicator for the prognosis of breast cancer patients, we further investigated associations between BACH1 and race, controlling for tumor grade and tissue type." (PMID 40710214, 2025). "Bioinformatics analyses support a negative association between the expression of the ETC gene and BACH1 expression in human breast cancer cells." (PMID 38321558, 2024). "We examined the association between scores of BACH1 (Allredscoretotal) or MCT1 (Hscoretotal3×2×1x) with clinical variables including: breast cancer subtypes, tissue types, tumor size, patient's racial/ethnic background, and age group." (PMID 37461502, 2023). "Our data indicate that the underlying mechanisms differ in ovarian and breast cancer cells, but involve destabilization of Bach1, AMPK activation, and induction of oxidative stress." (PMID 34807950, 2021). "Bach1 expression is linked to recurrence of breast cancer patients, and Bach1 promotes migration and invasion in colon and prostate cancer cells." (PMID 32793396, 2020). "Recent investigations have suggested that common genetic polymorphisms in BRCA1-associated C-terminal helicase 1 (BACH1) are important in the development of breast cancer." (PMID 24137204, 2013). "The subgroup analysis by the source of the cases indicated that there were significant correlations between the BACH1 919Ser polymorphism and a decreased risk of breast cancer in hospital-based and family-based studies." (PMID 24137204, 2013). "The aim of the present study was to update previous meta-analyses, as well as to provide a more comprehensive and reliable conclusion on the correlations between the BACH1 Pro919Ser polymorphism and breast cancer risk." (PMID 24137204, 2013). "Based on its interactions with BRCA1, the BACH1 gene is considered a potential breast cancer susceptibility gene." (PMID 24137204, 2013). "Further subgroup analyses revealed that there were significant correlations between the BACH1 919Ser polymorphism and a decreased risk of breast cancer in hospital-based and family-based studies." (PMID 24137204, 2013). "The aim of this meta-analysis was to derive a more precise estimation of the correlation between a common polymorphism [proline (Pro) 919 serine (Ser); rs4986764 C>T] in the BACH1 gene and susceptibility to breast cancer." (PMID 24137204, 2013). "The abnormal expression of BACH1 has been identified to be correlated with the risk of breast cancer due to its inability to mediate DNA recombination repair." (PMID 24137204, 2013). "Multiple germline mutations that disrupt Bach1 enzyme activity or BRCA1 association have been identified in breast cancer indicating Bach1 is a tumor suppressor." (PMID 22369660, 2012). "Taken together, our results are in concordance with previous studies where germ line BACH1 mutations have been observed in only a very few familial breast cancer patients." (PMID 16430786, 2006). "Genotypes of the BACH1 Ser919Pro variant among 866 unselected breast cancer patients and 731 healthy population controls." (PMID 16430786, 2006). "Previously, Cantor and co-workers have reported on BACH1 germ line missense mutations in early-onset breast cancer patients, with one of the patients having a strong family history of both breast and ovarian cancer." (PMID 16430786, 2006). "Tumor characteristics of the 909 breast tumors from 866 breast cancer patientsanalyzed for the BACH1 Ser919Pro variant." (PMID 16430786, 2006).
breast carcinoma (continued). "Our data suggest BACH1 as a distinct race-associated biomarker for breast cancer." (PMID 40710214, 2025). "Therefore, BACH1 mRNA expression has been associated with poor prognosis in breast cancer patients, particularly patients with basal-like TNBC tumors." (PMID 40710214, 2025). "For example, BACH1 expression level is associated with breast cancer recurrence in patients." (PMID 35651942, 2022). "Elevated levels of BACH1 expression have been linked to a higher risk of breast cancer recurrence in patients, whereas association with metastatic spread and poorer prognosis has recently been suggested in the case of human ovarian cancer and lung adenocarcinoma." (PMID 32132179, 2020). "Mutation in BACH1 or in BRCT domain that could disrupt the interaction between BRCA1 and BACH1, affect the HR pathway, delay DNA repair, and finally increase the risk of breast cancer." (PMID 33013205, 2020). "At present, a total of eight BACH1 truncating mutations have been identified worldwide, and the Pro919Ser polymorphism, which codes for amino acid 919 of the BACH1 protein, has been demonstrated to be closely correlated with breast cancer susceptibility." (PMID 24137204, 2013). "Therefore, the present meta-analysis was performed to provide a more comprehensive and reliable conclusion with regard to the correlation between the BACH1 Pro919Ser polymorphism and susceptibility to breast cancer." (PMID 24137204, 2013). "The analysis results suggested that no individual studies significantly affected the pooled OR of the correlation between the BACH1 919Ser polymorphism and breast cancer risk under the allele model, indicating that the results of the analysis were statistically reliable." (PMID 24137204, 2013). "Therefore, it was suggested that the BACH1 gene polymorphisms were functional and were correlated with breast cancer risk." (PMID 24137204, 2013). "Several studies have suggested that the BACH1 Pro919Ser polymorphism may be important in increasing susceptibility to breast cancer." (PMID 24137204, 2013). "However, genes of hot regions are linked to breast cancer disease such as BACH1, RAD51C, CYP24A1 and NCOA3." (PMID 23368971, 2013). "Certain previous case-control studies and a recent meta-analysis have suggested that the BACH1 Pro919Ser polymorphism may be important in the development of breast cancer." (PMID 24137204, 2013). "Together with previous studies, our results also indicate that although some rare germ line variants in BACH1 may contribute to breast cancer development, the contribution of BACH1 germline alterations to familial breast cancer seems marginal." (PMID 16430786, 2006). "This suggests that even though some functionally deleterious germ line BACH1 mutations have been observed in breast cancer patients, such mutations are rare and may account for only a very small proportion, if any, of non-BRCA1/2 familial breast cancer." (PMID 16430786, 2006). "In this study, we aimed to evaluate whether there are BACH1 genetic variants that contribute to breast cancer risk in Finland." (PMID 16430786, 2006). "In this study, we aimed to evaluate whether there are BACH1 genetic variants that contribute to breast cancer risk by screening the BACH1 gene for germ line alterations among 43 Finnish BRCA1/2 negative breast cancer families." (PMID 16430786, 2006). "In addition, we screened a further 399 and 253 cases, respectively, for specific regions of the FANCD2 and BRIP1/BACH1 genes that contained functionally important domains, or variants previously found in the germline of breast cancer cases." (PMID 16280053, 2005). "On the basis of our findings that the Keto diet may increase the risk of tumor metastasis in breast cancer, it may be more efficient to combine the use of the Keto diet with BACH1 inhibition, as we have proven that BACH1 deficiency can block Keto diet–induced metastasis." (PMID 38838145, 2024).
breast carcinoma (continued). "Furthermore, the results of the present meta-analysis suggested that the BACH1 919Ser polymorphism may be correlated with a decreased risk of breast cancer in females with a family history of breast cancer and without BRCA1/2 mutations." (PMID 24137204, 2013). "Furthermore, monoallelic mutations in the BACH1 gene have been demonstrated to be the predominant factor leading to the overexpression of BACH1, and these mutations may increase the hereditary breast cancer susceptibility." (PMID 24137204, 2013). "SNHG5 has also been shown to enhance glycolytic flux in breast cancer through the miR-299/BACH1 axis, promoting the expression of glycolytic enzymes such as HK2, PFK1, and GAPDH." (PMID 41550840, 2026). "BACH1 has been identified as a functional regulator of cancer metastasis and metabolic signaling in breast cancer cells." (PMID 40710214, 2025). "Our results showed that paeoniflorin, at similar non-toxic doses as those used in the transcriptomic analysis, reduced the levels of BACH1 (total, nuclear and cytoplasmic levels) in lung and breast cancer cell lines." (PMID 40716152, 2025). "BACH1 mRNA has been known to promote breast cancer metastasis and predict the survival of breast cancer patients." (PMID 40710214, 2025). "As BACH1 mRNA levels predict breast cancer patient’s outcomes, BACH1 protein levels have potential as a biomarker to stratify cancer patients." (PMID 40710214, 2025). "Mutations of BACH1 or BRCA1 affect the DNA repair process negatively and also result in a higher risk for breast cancer." (PMID 39621070, 2025). "Our BACH1 IHC analyses, along with complementary gene expression data from breast cancer patients, suggest that BACH1 is a distinct protein for TNBC." (PMID 40710214, 2025). "Given the described RKIP‐BACH1 feedback loop in breast cancer, we also assessed BACH1 protein and mRNA expression levels in our models." (PMID 40720248, 2025). "Our study provides compelling evidence that BACH1 expression is evident based on the race and subtypes of breast cancer patients." (PMID 40710214, 2025). "The depletion of BACH1 expression in cancer cells was sufficient to reduce the migration, invasion, intravasation, and metastasis of breast cancer." (PMID 40710214, 2025). "Multiple microRNAs (miRs) were found to target the post-transcriptional regulation of BACH1 and reduce cancer progression, such as miR-142-3p, which can target BACH1 in breast cancer cells, leading to reduced cellular proliferation, invasion, and migration." (PMID 38255314, 2024). "Together, our results underscore the pivotal role of ATF4, in collaboration with BACH1, in shaping the transcription of pro-metastatic genes and metastatic capacity of breast cancer cells under Keto diet condition." (PMID 38838145, 2024). "In breast cancer, BACH1 inhibits the expression of ETC complex (I-IV) genes and the activity of pyruvate dehydrogenase (PDH) via pyruvate dehydrogenase kinase (PDK), thereby decreasing mitochondrial metabolism." (PMID 38321558, 2024). "BACH1 is upregulated in breast and other types of cancer; it is proposed to be a marker of poor prognosis and a high metastatic rate in breast cancer." (PMID 38255314, 2024). "In breast cancer, bioinformatic analysis indicated that BACH1 mediates four Bone Marrow Signature (BMS) genes, including MMP1, CXCR4, FHL1, and DUSP1." (PMID 38321558, 2024). "BRIP1 gene was closely related to the function of breast cancer susceptibility BRCA1 (breast cancer 1, early onset), also known as BACH1 or FANCJ, located on 17q22-q24, about 18Kb, composed of 20 exons and 19 introns." (PMID 39211736, 2024). "Breast cancer cell line RNA sequencing (RNA-seq) data indicate higher BACH1 and lower RKIP expression in TNBC cell lines, suggesting TNBC-specific alterations of this regulatory network." (PMID 37231268, 2023). "For example, hemin specifically degrades BACH1 with negligible toxicity, inhibits breast cancer growth, and is used to treat patients with acute porphyria." (PMID 37228820, 2023).
breast carcinoma (continued). "We also looked at the expression of the transcription factor, BTB and CNC homology 1, BACH1, which has a role in metastasis, angiogenesis, and development of aggressive behavior of breast cancer cells." (PMID 36873936, 2023). "While RKIP belongs to the ‘team’ promoting an epithelial and tamoxifen-sensitive cell state in breast cancer, BACH1 is a part of the ‘team’ enabling a mesenchymal and tamoxifen-resistant phenotype." (PMID 37963558, 2023). "These trends were recapitulated in ER+ breast cancer datasets, where BACH1 also correlated negatively with ESR1 (estrogen receptor), but RKIP correlated positively with it." (PMID 37963558, 2023). "BACH1 promotes the invasion and metastasis in prostate cancer, colorectal cancer, ovarian cancer, breast cancer, pancreatic cancer, non-small-cell lung cancer and ESCC." (PMID 36670112, 2023). "BACH1 regulates cancer cell invasion genes, aiding in the migration and invasion of breast cancer cells, whereas acetyl tricyclic bis (cyanoketone) can produce novel activity and destroy BACH1 expression." (PMID 37686305, 2023). "MiR-142-3p, another miRNA associated with the metastatic stages of breast cancer, targets BTB domain and CNC homolog 1 (BACH-1)." (PMID 35884446, 2022). "MiR-142-3p reduced cell proliferation, invasion and migration of human breast cancer by regulating BACH1 expression." (PMID 34351577, 2022). "RKIP expression in prostate and breast cancer is initiated primarily by binding of the transcription factors BACH1 and SNAIL 1 to the RKIP promoter which suppresses RKIP transcription and expression." (PMID 36291854, 2022). "Compared with normal tissues, the expression of BACH1 protein is upregulated in primary cancer tissues of breast cancer, KIRC, UCEC and LUAD." (PMID 35651942, 2022). "To further investigate the potential mechanism of SNHG5 in breast cancer development, we firstly detected miR-299 and BACH1 levels after transfecting with sh-SNHG5 in BC cells." (PMID 34351577, 2022). "The specific degradation of BACH1 by panhematin (an FDA-approved drug) can effectively enhance the sensitivity of breast cancer cells to metformin treatment in vitro and in vivo." (PMID 33816265, 2021). "BACH1 promotes the expression of matrix metallopeptidase: it directly activates the expression of MMP1 in breast cancer cells and possibly MMP9 as well." (PMID 34339740, 2021). "As a transcriptional factor, BACH1 inhibits transcriptional expression of genes involved in mitochondrial oxidative phosphorylation (OXPHOS) of breast cancer cells as observed by reverse-transcriptase quantitative PCR (qRT-PCR) and protein blotting." (PMID 33809182, 2021). "For example, knockdown of the Bach1 gene suppresses the invasion of breast cancer cells by targeting the expression levels of matrix metalloproteinase-9 and CXCR4 receptor." (PMID 34949193, 2021). "For the post-transcriptional gene expression regulation, let-7 miRNA is known to suppress BACH1 levels by interacting with the 3′ untranslated region (UTR) of BACH1 in breast cancer cells and hepatocytes." (PMID 33809182, 2021). "Bach1 has been shown to function as an inducer of metastatic genes in breast cancer, including CXCR4 and MMP1." (PMID 34949193, 2021). "BACH1 represses oxidative phosphorylation in breast cancer cells, which is consistent with a glycolytic pattern of gene expression in metastatic triple-negative breast cancer cells." (PMID 34339740, 2021). "In our study, analysis of MAFF binding proteins using mass spectrometry identified a significant interaction between MAFF and BACH1 in breast cancer cells." (PMID 34262028, 2021). "In particular, basal-like breast cancer or triple-negative breast cancer (TNBC) subtype displays distinctive levels of BACH1 transcripts when compared with other breast cancer subtypes such as luminal A, luminal B, or her2-positive subtypes." (PMID 33809182, 2021).